INS (insulin)
Diseases named in the same sentence as INS in open-access papers (continued):
Sharing a sentence is not in itself a finding about the gene and the disease.
diabetes (continued). "Type 2 diabetes mellitus (T2DM), resulting from defective insulin secretion, resistance to insulin action or both, is associated with long-term complications affecting the eyes, kidneys, heart and nerves." (PMID 29296174, 2017). "In the present study, pre-diabetes was indicated by HOMA-IR as early as 4 weeks of intervention with greater plasma glucose HbA1C and insulin in HFF mice compared to LF controls." (PMID 29249964, 2017). "The effect of diabetes on circulating neutrophil MMP-9 and NGAL and the effect of insulin treatment was also studied." (PMID 28182694, 2017). "Diabetes mellitus (DM), currently characterized by symptoms of chronic hyperglycaemia, is a syndrome defined as a state of dysregulation of glucose homeostasis and lipid metabolism due to beta cell dysfunction or insulin resistance." (PMID 28132388, 2017). "Diabetic ketoacidosis (DKA) occurs in 20-40% of children and adolescents with new-onset type 1 diabetes mellitus (T1DM) and after DKA resolves, the therapy is switched to any insulin regimen that aims to control blood glucose (BG) levels." (PMID 28044993, 2017). "The term diabetes mellitus (DM) describes a metabolic disorder of multiple etiologies characterized by chronic hyperglycemia, with carbohydrate, fat, and protein metabolism disorders resulting from defects in insulin secretion or action." (PMID 28400914, 2017). "This risk was similar whether or not the diabetes was insulin-treated." (PMID 28197657, 2017). "On the other hand, type 2 diabetes mellitus (T2DM), which accounts for less than 90% of diabetes cases, involves insulin resistance in peripheral tissues and increased levels of blood glucose due to overnutrition accompanied by deficient insulin secretion." (PMID 29036909, 2017). "For type-2 diabetes mellitus (T2DM), several types of therapeutic approaches are taken into account, viz., improving insulin secretion by the pancreas, ameliorating the sensitivity of insulin to target receptor or increasing glucose uptake in adipocyte cells." (PMID 28854906, 2017). "Insulin resistance is a characteristic feature of diabetes, obesity, and NAFLD, which is characterized by the decreased tissue sensitivity to the biological effect of insulin and leading to compensatory insulin releasing." (PMID 28458689, 2017). "We demonstrated that saxagliptin treatment improved pancreas insulin secretion capacity and increased β-cell area through increasing SDF-1α levels in the HFD/STZ-induced diabetic rats." (PMID 29230196, 2017). "In type 2 diabetes mellitus (T2DM), however, there is an imbalance in insulin secretion and blood sugar absorption." (PMID 28445415, 2017). "This study assessed the activation of CD4+ and CD8+ T-lymphocytes by human insulin and human glutamate decarboxylase (GAD) in patients with type 1 or type 2 diabetes mellitus (DM) and healthy volunteers." (PMID 28986401, 2017). "On the other hand, patients with diabetes without known lung disease also may show a decreased CO diffusing capacity, and impairment of pulmonary function in type I diabetes patients treated with insulin was linked to the quality of metabolic control." (PMID 28086884, 2017). "On the other hand, experimental studies also showed that PRL has effects on growth of pancreatic ß-cells and reduces threshold for glucose-stimulated insulin secretion, which indicate that PRL has a protective effect against type 2 diabetes mellitus." (PMID 28384295, 2017). "Type 2 diabetes mellitus (T2DM) is characterized by insulin resistance and failure of producing insulin on pancreatic beta cells." (PMID 28612706, 2017). "We also applied the cost of metformin therapy for diabetes in the UK, which was approximately one-third of the costs of multiple insulin injection therapy (4.18 million JPY/patient) or conventional insulin injection therapy in Japan (4.40 million JPY/patient)." (PMID 28957385, 2017).
diabetes (continued). "In all, 214 (47.3%) participants were insulin resistant, with 88.7% of them on ART and 9.9% having diabetes." (PMID 28797289, 2017). "Compared with quantile 2 (Q2) of insulin, the adjusted prevalence odds ratios (POR) for diabetes were 2.3 (95% CI: 0.5–10.1) and 12.2 (95% CI: 3.3–45.5) (P for trend = 0.0003) for quantiles 3 (Q3) and 4 (Q4), respectively." (PMID 28753646, 2017). "Median admission blood glucose levels 244 mg/dL (IQR 166–368 mg/dL) for patients receiving insulin detemir and 226 mg/dL (IQR 172–314 mg/dL) for patients receiving insulin glargine (p = 0.61) were present even though most were known to have diabetes mellitus." (PMID 28970434, 2017). "The meta-analysis results showed that the PGRMC1 were significant across diabetes studies, presenting six out of 13 studies with the U-score ≤ 0.05, and the IRS1 gene was significant in four studies of insulin response (i.e., U-score ≤ 0.05)." (PMID 28117714, 2017). "When insulin secretion is insufficient and blood glucose levels rise, IGT and diabetes ultimately become overt." (PMID 28372564, 2017). "Our analysis showed that PGRMC1 and HADH genes were significant over diabetes studies, while IRS1 and MPST genes were significant over insulin response studies, and joint analysis showed that HADH and MPST genes were significant over all combined data sets." (PMID 28117714, 2017). "Longer time to peak glucose level during an OGTT was associated with higher HbA1c, increased glucose AUC, reduced total insulin secretion and thus a greater likelihood of IPH and diabetes." (PMID 29216249, 2017). "The dysfunction of insulin-stimulated GLUT4 translocation is highly related to peripheral insulin resistance and non-insulin-dependent diabetes mellitus in human beings." (PMID 28529958, 2017). "The purpose of this work was to assess the influence of novel GPR119 agonist ZB-16 on the glucose utilization, insulin, and glucagon-like peptide-1 (GLP-1) secretion and the morphology of pancreas in rats with streptozotocin–nicotinamide-induced diabetes." (PMID 28736546, 2017). "Studies in women with diabetes demonstrated that fewer women required treatment with medication when exposed to GPC, and for those requiring treatment with insulin, GPC individuals required less than half the dose." (PMID 28962601, 2017). "Sixteen studies were found that investigated SES and at least one aspect of diabetes management (glycaemic control, self-monitoring of blood glucose levels (SMBG), insulin regimens or access to specialist diabetes care)." (PMID 28489876, 2017). "With respect to the treatment of diabetes, the population admitted to the SHC unit in this study showed a lower frequency of insulin use when compared to countries such as Germany, Italy, Sweden, United Kingdom and to Brazilian studies." (PMID 29129980, 2017). "Diabetes management (glycaemic control, self-monitoring of blood glucose levels (SMBG), access to specialist care (SC) and adoption of an intensive insulin regimen)." (PMID 28489876, 2017). "The treatment depends on the type of diabetes; however, in case of T1DM and over time in T2DM this means external insulin administration by insulin pen (manual) or insulin pump (semiautomated)." (PMID 32025098, 2017). "In addition, diabetes-related characteristics including; frequency of self-monitoring of blood glucose, diet, diabetes duration, regularity of clinic visits, insulin regimen and family involvement in diabetes related tasks are also associated with the level of glycaemic control of patients." (PMID 28606170, 2017). "It has already been a confirmed fact that obesity causes insulin resistance (affect insulin action), and decreases insulin-stimulated glucose disposal, leading to the development of IFG and diabetes mellitus consecutively." (PMID 28683811, 2017).
diabetes (continued). "], 240 patients with diabetes and glucose ≥140 mg/dL were included at hospital admission for AMI and randomized to strict glycemic control (target glycemia 72–180 mg/dL) with insulin plus intravenous glucose infusion for at least 24 h or conventional therapy." (PMID 28725272, 2017). "Reductions in FG of 0.1 mmol/L in the Metformin in Gestational Diabetes Trial and 0.3 mmol/L in a large RCT were observed when insulin was compared to anti-hyperglycemic medications in pregnant women." (PMID 28771519, 2017). "For instance, pparg agonists, which are insulin-sensitization drugs such as thiazolidinedione (TZD), are widely prescribed to diabetes mellitus 2 patients." (PMID 28704398, 2017). "In patients with type 1 diabetes mellitus (T1DM), glucose dynamics are influenced by insulin reactions, diet, lifestyle, etc., and characterized by instability and nonlinearity." (PMID 28740090, 2017). "This later has been reported in the Diabetes Control and Complications Trial (DCCT) where this occurred in 13.1% of the intensive group (using intensive insulin therapy) versus 7.6% of the conventional treatment group (using conventional insulin regime)." (PMID 29017477, 2017). "In fact, there are many clinical indicators to classify diabetes, such as the test results of Oral Glucose Tolerance Test (OGTT), INS, C-Peptide, IAA, ICA." (PMID 29234049, 2017). "Type 2 diabetes mellitus (T2DM) is a chronic degenerative disease characterized by hyperglycemia, mainly due to defects of insulin secretion and/or action." (PMID 28397755, 2017). "Type 2 diabetes mellitus (T2DM) is a chronic condition characterized by excessive glucose levels, resulting from insulin resistance and/or decreased insulin secretion." (PMID 26853601, 2017). "However, this may be even more important in people with diabetes, as different vitamins and minerals play a relevant role in the regulation of glucose metabolism at different levels (insulin action, oxidative stress, and inflammation) and in the prevention of diabetes complications." (PMID 29109962, 2017). "GIP is elevated in type 2 diabetes mellitus and in impaired glucose tolerant patients while GLP-1 improves insulin sensitivity in mice and humans." (PMID 28085952, 2017). "In the United Kingdom Prospective Diabetes Study (UKPDS) study, patients gained 6 kg with insulin therapy, when compared with 1.7–2.6 kg weight gain with sulfonylureas." (PMID 28167928, 2017). "Abnormally elevated glucagon secretion in diabetes can be reproduced by high-glucose treatment of InR1G cells, and the involvement of high glucose-oxidative stress-JNK-insulin signaling pathway axis has been demonstrated." (PMID 28426798, 2017). "Type 2 diabetes mellitus (T2DM) is a multifaceted heterogeneous group of metabolic disarray with hyperglycemia and defective insulin action and/or insulin secretion." (PMID 28367665, 2017). "Among them, EN-RAGE is a novel inflammatory marker for pre-diabetes, IL17 for incident T2D and IL13 for pre-diabetes, incident T2D and insulin therapy start." (PMID 28258520, 2017). "Although guinea pigs have been previously used as a diabetes model only through induction with STZ, this serves specifically as a model of insulin-dependent diabetes because it lacks the contribution of insulin resistance." (PMID 28093504, 2017). "Various studies in placental tissue suggest that diabetes mellitus alters the expression of glucose transporter (GLUT) proteins, with insulin therapy being a possible modulatory factor." (PMID 27981520, 2017). "Hypothalamus plays a significant role in the control and maintenance of plasma glucose and insulin secretion, indicating that stimuli or insults induced during the growth of brain during the perinatal period may play a major role in the pathogenesis of diabetes." (PMID 28824543, 2017).
diabetes (continued). "The lack of association between metabolic control and reduced diastolic function in this study could indicate that the early reduced diastolic function in children with diabetes is partly caused by factors presented before the start of insulin treatment, and not reflected by HbA1c measured later." (PMID 28545398, 2017). "Its beneficial roles in regulating insulin sensitivity and glucose homeostasis make FGF21 a promising therapeutic candidate for the treatment of diabetes." (PMID 28770320, 2017). "Many factors may be implied in the low frequency of good metabolic control among patients with diabetes, but it is likely that one of the main reasons may be PCPs’ lack of knowledge and confidence on several aspects of DM management, specially regarding insulin use." (PMID 28279950, 2017). "At this time, NOD mice in the control arm were treated with LinBit insulin pellets and randomised to bi-weekly therapeutic injections of either PBS or IL-22 (200 ng/g) and followed until overt diabetes was diagnosed, as defined above." (PMID 28779211, 2017). "Therefore, an exacerbated production of ketone bodies and the subsequent development of ketoacidosis could be expected to appears in the absence of carbohydrates and a completely insulin-deficient condition in predisposed subjects." (PMID 28914421, 2017). "Peripheral blood mononuclear cells (PBMCs) from 18 patients with type 1 diabetes mellitus were taken at baseline and 12 months after AHSCT or insulin-only therapy." (PMID 28420440, 2017). "Additionally, in diabetes, the mRNA available for α-amylase production in the exocrine acini of the colon decreases, thereby decreasing the synthesis of α-amylase; it has been reported that injection of insulin into diabetic mice increases the colonic excretion of α-amylase." (PMID 27927080, 2017). "The Diabetes Control and Complications Trial (DCCT) study demonstrated that nearly 20% of patients receiving insulin pump therapy had symptomless nocturnal hypoglycemia." (PMID 28271075, 2017). "Other forms of DM, classified on the basis of insulin secretion profile and/or onset, include Gestational Diabetes, endocrinopathies, MODY (Maturity Onset Diabetes of the Young), neonatal, mitochondrial, and pregnancy diabetes." (PMID 28138367, 2017). "Insulin is a vasodilator at the arterial, venous, and microcirculatory levels and insulin resistance has been shown to be related to coronary microvasculature abnormalities in patients without diabetes, suggestive of an important underlying mechanism in onset of this disease." (PMID 28448601, 2017). "Mean levels of glucose and insulin remained significantly higher in those with EDS (p=0.03 and 0.01, respectively) even after further adjustment for prevalent diabetes and night-time sleep." (PMID 28674146, 2017). "Thus, insulin analogs with a preferential binding to IR-B could have increased or preferential hepatic bioactivity in vivo and could be significant in the treatment of diabetes, with a more physiological profile of action." (PMID 28798723, 2017). "We prefer Phenotype 1 = {hypertension, ACE inhibitors}, Phenotype 2 = {diabetes, insulin} to Phenotype 1 = {hypertension, ACE inhibitors, insulin}, Phenotype 2 = {diabetes}, because the former is more distinct and meaningful than the latter." (PMID 28442772, 2017). "Type 2 diabetes mellitus (T2DM) is characterized by increased insulin resistance, depleted insulin secretion and subsequently elevated levels of blood glucose." (PMID 27909794, 2017). "Diabetes is commonly classified into two types; type 1 is due to auto-immune damage to pancreatic β-cells, leading to a complete deficiency of insulin; type 2 is caused by insulin resistance, i.e., the cells do not respond to insulin stimulation, as well as β-cell dysfunction." (PMID 29209160, 2017). "Type 2 diabetes mellitus (T2DM) is a disease resulting from impairments in insulin action and insulin secretion." (PMID 28862678, 2017).
diabetes (continued). "We analysed the most relevant common neonatal diabetes genes (KCNJ11, ABCC8, INS) to exclude monogenic diabetes in infancy-onset diabetes (n = 8 patients with manifestation before age 12 months)." (PMID 28534863, 2017). "Diabetes mellitus was defined as a prior clinical diagnosis of diabetes, use of anti-hyperglycemic medications including insulin, or an electronic medical record (EMR) or problem list-based diagnosis of diabetes." (PMID 28738059, 2017). "Then she was diagnosed as ketosis-prone type 1 diabetes mellitus (KPD), the treatment was switched to the insulin aspart 30 and later a long-acting insulin analogue (glagine), and she got a well blood glucose control." (PMID 28105082, 2017). "We therefore assessedthe cardiometabolic phenotype of 340 men with type 2 diabetes mellitus (T2DM) in relation to Lp(a), focusing on BCF and hyperbolic product [BxS], which adjusts BCF to insulin sensitivity and secretion." (PMID 28899393, 2017). "To investigate the activation of autoreactive CD8+ T cells and the onset of diabetes, we infected transgenic splenectomized and sham mice expressing the LCMV glycoprotein under control of the rat insulin promoter (RIP-GP) (as controls) with LCMV." (PMID 28239381, 2017). "In a type 2 diabetes mellitus mouse model (db/db), oral administration of geraniol improved glucose homeostasis by increasing plasma GLP-1 and insulin levels." (PMID 29070885, 2017). "Type 2 diabetes mellitus (T2DM) is a complex metabolic disorder which is characterised by abnormal hepatic glucose production, insulin resistance, and impaired pancreatic insulin secretion." (PMID 28348587, 2017). "Recently, the Human Diabetes Proteome Project (HDPP) was launched with an initial focus on islets of Langerhans, insulin-producing cell lines, and blood samples from diabetes-related patient cohorts." (PMID 28752056, 2017). "Deterioration of insulin response measured as peak C-peptide and the 2 h glucose value during an OGTT seem to accelerate in the months before diabetes diagnosis." (PMID 28550517, 2017). "In addition, TNF-α inhibitor treatment may decrease the risk of diabetes mellitus in patients with psoriasis, and improve insulin sensitivity both in diabetic and non-diabetic patients." (PMID 29065479, 2017). "Since diabetic nephropathy is one of the complications of longterm diabetes, glycemic control has also been evaluated in an acute as well as subchronic setting in STZ-rats treated with insulin including the analysis of renal parameters." (PMID 27253523, 2016). "Increase in the incidence of Insulin Dependent Diabetes Mellitus (IDDM) among people from developed and developing countries has created a large global market for insulin." (PMID 27579308, 2016). "High-intensity exercise has mixed effects for diabetes patients: improved body composition, physical fitness, GLUT4 protein expression, mitochondrial function, oxygen capacity, and, to some extent, insulin sensitivity." (PMID 27073714, 2016). "Insulin resistance (IR) and impaired insulin secretion are the main pathogeneses in impaired glucose tolerance (IGT) and type 2 diabetes mellitus (T2DM)." (PMID 26770991, 2016). "Therefore, maternal intrauterine milieu may alter the metabolic status of the fetus, instigating an insulin resistance state and enhancing the development of type 2 diabetes mellitus and metabolic syndrome in the adult life, especially following postnatal obesogenic environment." (PMID 27200209, 2016). "Diabetes mellitus (DM), especially Type-2 DM (T2DM), one the most common metabolic disorders worldwide, is due to faults in insulin secretion, or its action, or both." (PMID 28036014, 2016). "A significant increase in fasting insulin level was observed in diabetic rats compared to control rats (p < 0.01); and CDC treatment prevented the diabetes-induced increase in fasting insulin level (p < 0.05)." (PMID 27164093, 2016).